ARID1A (AT-rich interaction domain 1A)
Diseases named in the same sentence as ARID1A in open-access papers (continued):
Sharing a sentence is not in itself a finding about the gene and the disease.
tumor (continued). "AT-rich Interactive Domain-containing protein 1A (ARID1A) acts as a tumor suppressor gene, its mutations being linked to PD-L1 upregulation." (PMID 39940924, 2025). "Loss of Arid1a promoted prostate tumorigenesis, with rapid tumour formation and altered tumour morphology (less differentiated epithelial compartment and reduced/disorganised stroma)." (PMID 39885328, 2025). "Conversely, in the low-risk group, PIK3CA, PTEN, and ARID1A exhibit the highest mutation frequencies, suggesting a correlation with the initial stages of tumor development." (PMID 40463372, 2025). "Loss of function of ARID1A results in genomic instability, accumulation of mutations, and tumor initiation with uncontrolled cell proliferation." (PMID 41514650, 2025). "The loss of ARID1A in tumour cells triggers anti‐tumour immunity by activating the STING‐I type interferon pathway via the R‐loop‐derived cytoplasmic DNA." (PMID 39779467, 2025). "Tumors harboring ARID1A mutations tend to exhibit high microsatellite instability or high tumor mutational burden, suggesting increased sensitivity to immune checkpoint inhibitors." (PMID 41008893, 2025). "Here, we show that ARID1A loss results in a biologically and clinically relevant immune evasive phenotype in FL by rendering tumor cells resistant to FASLG-induced apoptosis." (PMID 39843653, 2025). "We have shown that a low ARID1A expression in the tumor tissue of GC patients is significantly associated with a large primary tumor size (T3 + T4) (p = 0.037)." (PMID 39796161, 2025). "It indirectly promotes tumorigenesis by downregulating the tumor‐suppressive ARID1A and its associated transcriptome, and it directly activates pro‐oncogenic pathways such as inflammatory signaling and EMT." (PMID 40671262, 2025). "For example, the loss of ARID1A in T24 tumor cells led to strong activation of most of these pathways, while they were only weakly affected in the normal‐like cell lines." (PMID 40170512, 2025). "As a tumor suppressor, ARID1A loss-of-function mutations enhance migratory and invasive capacities of NB cells through cell cycle dysregulation, thereby promoting tumor cell proliferation." (PMID 41001036, 2025). "Arid1a loss mediated tumour formation in the mouse involved both the anterior and dorsoateral lobes, a key distinction from Pten-loss driven tumours which tend to be limited to the anterior lobes." (PMID 39885328, 2025). "Loss of ARID1A function can lead to more aggressive tumor behavior and plays a key role in DNA repair and chromatin remodeling, meaning its mutation can promote tumorigenesis." (PMID 40729021, 2025). "Chromatin remodeling gene mutations were identified in 9 of 17 tumors (53%), involving BAP1 mutations in 6 tumors (35%), SETD2 mutations in 4 tumors (24%), and an ARID1A mutation in 1 tumor (6%)." (PMID 40940841, 2025). "Cancer cell-intrinsic type I IFN levels were also dramatically increased by radiation and CHK1 inhibition through the cGAS/STING axis, which in turn reshaped the tumor microenvironment within ARID1A-deficient tumors." (PMID 40750787, 2025). "Our data revealed that homozygous Arid1a loss is required to dramatically accelerate prostate tumourigenesis, resulting in tumours with a reduced and disorganised stroma." (PMID 39885328, 2025). "Future research is warranted to fully defined molecular events that would interact with shallow loss of ARID1A in clinical tumours." (PMID 39885328, 2025). "Emerging evidence has implicated ARID1A dysregulation in tumor progression through multifaceted interference with DNA damage repair mechanisms." (PMID 41215803, 2025).
tumor (continued). "As a tumor suppressor, ARID1A loss is correlated with tumor progression, with its frequency increasing with tumor-node-metastasis (TNM) stage: 7.4% in stage I, 24.1% in stage II, 22.2% in stage III, and 46.3% in stage IV." (PMID 41360780, 2025). "ARID1A has previously been reported to be associated with enhanced cancer stemness characteristics and tumor immune evasion when mutated." (PMID 40240758, 2025). "A similar analysis of associations between the expression of ARID1A, miR-129-5p and miR-3613-3p and their clinical and pathological characteristics was also performed in non-tumor tissues of the same GC patients." (PMID 39796161, 2025). "Biomarkers such as PD-L1 CPS ≥ 1%, ARID1A mutations, elevated tumor mutational burden, and PIK3CA alterations emerge as promising predictors of therapeutic response." (PMID 41020848, 2025). "All in all, we found that ARID1A deficiency impacts several cellular processes that are relevant for tumor formation, including cell proliferation, EMT, cell cycle checkpoints, splicing, and immune response." (PMID 40170512, 2025). "In this study, we observed a significant increase in the expression of PD-L1 in ARID1A-deficient tumor cell." (PMID 39773749, 2025). "The decreased level of ARID1A protein in GC patients was associated with an increase in tumor invasion and, thus, with the progression of the disease rather than the early stages." (PMID 39796161, 2025). "Some drugs, such as ATM inhibitors, simvastatin and aspirin, act synergistically with PD-L1 inhibitors to inhibit tumor growth in ARID1A-deficient mice." (PMID 40406134, 2025). "First, while our in vitro models established mechanistic causality for ARID1A hypermethylation in driving immune evasion, they cannot fully replicate dynamic tumor-immune interactions." (PMID 41215803, 2025). "ARID1A is a tumor suppressor gene whose mutations, characterized by loss of staining in tumor cells, are implicated in the pathogenesis of EEC." (PMID 41001390, 2025). "Reduced expression of ARID1A is significantly associated with tumor progression, metastasis, and poor overall survival in both human and murine models." (PMID 40699663, 2025). "Previously, we conducted genome-wide next-generation sequencing of 81 HCC tissue samples and found that ARID1A alterations were significantly correlated with a higher tumour mutation burden in HCC." (PMID 38166741, 2024). "Tumor inflammation, ARID1A loss, and genome instability are among the most promising areas for future study." (PMID 37934611, 2024). "Contrariwise, in the tumor harboring the ARID1A variant, angiogenesis was up-modulated while fatty acid metabolism was down-modulated." (PMID 39408812, 2024). "Cases with high ARID1A mutation abundance in both tumor (OS, P < 0.001; PFS, P < 0.001) and blood samples (OS, P < 0.001; PFS, P = 0.024) significantly had worse survival." (PMID 38378604, 2024). "The study also demonstrated that mutations in the gene ARID1A were associated with microvascular invasion in the tumour, and that patients with microvascular invasion had significantly larger tumours than patients without." (PMID 38536546, 2024). "Alterations in ARID1A are associated with a higher tumor mutation burden in various cancers, making such cancers or subtypes potentially more susceptible to immunotherapy." (PMID 39697230, 2024).
tumor (continued). "This led to increased mitochondrial respiration and rendered ARID1A-deficient tumor cells vulnerable to drugs that target the TCA cycle and/or oxidative phosphorylation." (PMID 38666605, 2024). "Further investigation of the immune cells infiltrating tumour tissues revealed multiple enriched immune signatures in the ARID1A-deficient group." (PMID 38166741, 2024). "Currently, most studies indicate that ARID1A is a tumor suppressor gene, and mutations and downregulation of the expression of this gene are associated with a poor prognosis for patients with tumors." (PMID 39322625, 2024). "ARID1A is mutated in ∼10% of all tumors with postulated balancing oncogenic and tumor suppressive functions." (PMID 39226899, 2024). "Early research focused on the tumour suppressor role of ARID1A and ARID1A deficiency, which are associated with worse prognostic outcomes in various cancers." (PMID 38166741, 2024). "In the absence of pharmacological treatment, ARID1A knockdown markedly decreased tumor clone development; under SR-4835 treatment, ARID1A-deficient cells demonstrated improved sensitivity to CDK13 inhibitors." (PMID 38835016, 2024). "We found durable clinical benefit in diverse tumor types, with evidence suggesting multiple potential biomarkers of response to ATRi, including loss of ARID1A, genomic instability, ATM/G1 pathway abnormalities, and high tumor inflammation." (PMID 37934611, 2024). "Two of these genes (NOTCH1 and ARID1A) were each targeted by two mutational events in two different tumours." (PMID 39766052, 2024). "Bitler and colleagues used an EZH2 inhibitor (GSK126) to treat ARID1A-loss OCCC cells and found that ARID1A mutation status correlated with the response of tumor cells to EZH2 inhibitors." (PMID 38347608, 2024). "The loss of condensate-competent ARID1A significantly impairs tumor progression, identifying it as a potential therapeutic target." (PMID 39344201, 2024). "Barcoding of SCLC tumor clones referring to a panel of 40 candidate genes revealed that Tsc1 and Pten inactivation resulted in increased tumor size, while Pcna/Arid1a alterations were associated with decreased TMB." (PMID 38395864, 2024). "Conversely, the loss of ARID1A during late-stage tumor growth hinders the transcription of genes linked to migration, invasion, and metastasis." (PMID 38365747, 2024). "ARID1A is believed to act as a tumor suppressor due to its loss-of-function mutations observed in many cancers, including gastrointestinal types, leading to a loss of protein expression." (PMID 39199659, 2024). "For the other genes, ARID1A was mutated in 14% and 9% of the tumor and blood samples, respectively, with high mutation abundance observed in 2% and 5% of the samples." (PMID 38378604, 2024). "In mouse models, ARID1A deficiency has been shown to accelerate tumor progression, leading to high-stage disease." (PMID 38893181, 2024). "ARID1A mutations can lead to genomic instability and reshape the tumor immune microenvironment (TIME), which can be used as a biomarker for immunotherapy." (PMID 38847966, 2024). "The direct or indirect inhibition of the PI3K/AKT/mTOR pathway leads to the synthetic lethality of ARID1A-deficient tumour cell clones." (PMID 38893278, 2024).
tumor (continued). "An OCCC patient with an ARID1A mutated tumour achieved a partial and sustained response to the combination of olaparib, pembrolizumab and bevacizumab." (PMID 39272926, 2024). "In patients with ARID1A-clonal expression deficiency tumor, the infiltration patterns of these three immune cell types were comparable to those in ARID1A-proficient patients." (PMID 38555560, 2024). "ARID1A is a tumor suppressor gene that encodes a subunit of the chromatin remodeling complex SWI/SNF." (PMID 38893118, 2024). "Overall, ARID1A is the most frequently mutated subunit with early reports suggesting a tumor suppressor role." (PMID 38358974, 2024). "Most ARID1A mutations observed are characterized as frame-shift or nonsense mutations, implying that ARID1A functions as a tumor suppressor." (PMID 38391958, 2024). "ARID1A mutations have been implicated in both tumor suppression and tumor initiation in many malignancies, including DLBCL." (PMID 38902256, 2024). "In patients with ARID1A-clonal expression deficiency tumor, the infiltration patterns of three immune cell types were comparable to those in ARID1A-proficient patients." (PMID 38555560, 2024). "There is little data on ARID1A as a prognostic indicator for EC, likely because loss of the gene occurs very early in the tumor formation process." (PMID 37465112, 2023). "Specifically, in LUAD, loss of ARID1A expression promotes tumor proliferation and metastasis in vitro and in vivo." (PMID 36869329, 2023). "Whereas, during the late stages of HCC progression, the ARID1A loss due to acquired mutations, elicits tumor escape and enhance cell proliferation." (PMID 36890819, 2023). "ARID1A gene also serves as a tumor suppressor and is frequently mutated in several cancers, including bladder, hepatic, colorectal and renal cancers." (PMID 38017409, 2023). "Once the tumours are established, ARID1A acts as a tumour suppressor via downregulation of metastasis-associated genes." (PMID 38275587, 2023). "We find that EAC tumors with ARID1A mutations are associated with enhanced tumor-infiltrating CD8+ T cell levels." (PMID 38001638, 2023). "Homozygous or heterozygous loss of ARID1A is tumor suppressive due to the decreased chromatin accessibility at enhancers and also decreased expression of genes linked to migration, invasion, and metastasis." (PMID 37093326, 2023). "For example, chromatin remodeler ARID1A is the second most frequently mutated gene of the cohort, mutated across tumor types at a rate of 8%." (PMID 37414794, 2023). "In some preclinical studies, however, AIRD1A inactivation was insufficient to be the sole driver mutation for tumorigenesis, with rare studies linking ARID1A loss to slower tumor initiation." (PMID 37109525, 2023). "The most frequent mutation type, ARID1A, was a truncating mutation, like a frameshift mutation, that leads to DNA damage repair defects in tumor cells." (PMID 37096801, 2023). "Intriguingly, ARID1A-deficient tumors display increased mutation load, upregulation of PD-L1 expression, and elevated numbers of tumor-infiltrating lymphocytes (TILs)." (PMID 36980292, 2023). "The most frequently mutated driver genes were RELN, CDH1 and ARID1A, identified in 75%, 65% and 40% of tumor samples, respectively." (PMID 36703611, 2023). "It is reported that loss of ARID1a up-regulated PTEN in terms of the tumor cell proliferation in endometrial glands." (PMID 36675190, 2023). "They conducted experiments on a large cohort and found high PD‐L1 expression in ARID1A‐deficient tumours." (PMID 38041544, 2023). "Mutations in ARID1A gene are usually responsible for its loss of function, thus suggesting a major tumor suppressive role." (PMID 36890819, 2023). "One widely accepted theory posits that ARID1A acts as a ‘caretaker’ gene, functioning as a tumour suppressor by preventing sequence mutations and chromosomal structural abnormalities." (PMID 38041544, 2023).
tumor (continued). "For example, loss of ARID1A was accompanied by decreased expression of several classical tumor suppressors, such as PIK3IP1, CDKN1A, TGF-b, SMAD3, and E2F4." (PMID 37371564, 2023). "In some cancers, ARID1A loss is associated with worse prognostic features, thus supporting a major tumor suppressive role." (PMID 36890819, 2023). "Loss of ARID1A expression is associated with higher-grade tumours and triple-negative status and predicts poorer response to paclitaxel in triple-negative breast cancer." (PMID 38275587, 2023). "The loss of ARID1A expression in human cancers is generally associated with negative prognostic features, tumor progression and increased tumor growth and invasion." (PMID 36890819, 2023). "The prevalence of ARID1A loss increases with the grade of the tumour, suggesting a role in tumour progression." (PMID 38275587, 2023). "ARID1A-mutated EC exhibit decreased PgR transcription levels, which are associated with changes in the PgR enhancer region during early tumor development." (PMID 37730563, 2023). "Another study reported that patients with ARID1A loss had a shorter cancer specific survival and a significant association of ARID1A loss to male sex, larger tumor size, smoker status and squamous histology." (PMID 36890819, 2023). "EBV-positive area showed no loss of ARID1A expression, whereas EBV-negative area showed loss of ARID1A expression on 60% of tumor cells." (PMID 37434198, 2023). "Immunohistochemical experiments further demonstrated higher levels of CD8 protein and significant upregulation of PDCD1 (which encodes the PD‐1 protein) in ARID1A‐depleted tumours." (PMID 38041544, 2023). "Mechanistically, ARID1A mutation correlated with extensive DNA damage repair deficiency and immunogenic tumor microenvironment (TME) featured by elevated activated subsets of CD8+ T cells, CD4+ T cells, and NK cells." (PMID 36369379, 2023). "In summary, more relevant to clinical applications, BRD4i-ATRi treatment causes complete tumor regression in chemotherapy-resistant CCOC PDX tumors more so than monotherapy in an ARID1A level-dependent manner." (PMID 37841875, 2023). "Mutations in the ARID1A gene can impair tumor-suppressing functions, allowing cells to divide and proliferate uncontrollably." (PMID 38203635, 2023). "ARID1A is a tumor suppressor gene, encoding for BAF250a, a subunit of the SWI/SNF chromatin-remodeling complex, which alters the accessibility of chromatin to different nuclear factors, thereby preventing genomic instability." (PMID 37627318, 2023). "Recent advances, including CRISPR/Cas9-based gene editing, have made possible systematic screens for synthetic lethal targets in human cancers harboring mutations of tumor suppressor, such as ARID1A." (PMID 36980292, 2023). "On the other hand, ARID1A expression loss triggers a variety of pathways related to tumor progression and metastasis, including the ErbB pathway, VEGF pathway, HIF-1 pathway and RAF1 pathway, to participate in metastasis." (PMID 36869329, 2023). "There is evidence that ARID1A can modulate the tumor immune microenvironment, which underlies its correlation with sensitivity to immunotherapy." (PMID 37981695, 2023).